MYC (MYC proto-oncogene, bHLH transcription factor)
Diseases named in the same sentence as MYC in open-access papers (continued):
Sharing a sentence is not in itself a finding about the gene and the disease.
tumor (continued). "Considered together, these data suggest that MYC is an essential regulator of the mitochondrial RNA polymerase POLRMT in a broad array of tumor cell lineages." (PMID 27590350, 2016). "Testing discriminant isoforms for each stage class and tumor type independently yielded frequent enrichment of MYC targets, oxidative phosphorylation, mTORC signaling, DNA repair, and Interferon response." (PMID 27535130, 2016). "BL is a paradigm of a c-MYC-addicted human tumour resulting from chromosomal translocations placing c-MYC under the control of Ig regulatory sequences leading to c-MYC overexpression." (PMID 26729287, 2016). "In this particular case, MYC overexpressing tumour cells appear to be reliant upon the activity of the inhibitor of apoptosis protein (IAP), BIRC5 (survivin) a CDK1 target." (PMID 26881434, 2016). "At the genomic level, gains of MYC locus and losses of MAX (Myc-associated factor X), a negative regulator of MYC18, were more frequent in O1 than in O2 and O3 tumours (t-test P values=0.02 and 0.0002, respectively)." (PMID 27090007, 2016). "The proportion of tumor cells expressing MYC (i.e., MYC IHC score) was estimated as 18.16 ± 19.58 % (mean ± SD) (median: 10, range: 0-80 %)." (PMID 27286976, 2016). "In fact, GLS1 inhibition is a good strategy for tumor cells that overexpress MYC and thus present glutamine dependence." (PMID 28040803, 2016). "Possibly offering the most important contribution to a major metabolic switch in tumor tissue, MYC strongly influences glutamine metabolism (Key factor 3) by regulating glutaminase (GLS) expression through miRNAs." (PMID 27590516, 2016). "On the other hand, MYC was shown experimentally to induce fatty acid oxidation through mitochondrial biogenesis, such that shutting down MYC expression resulted in accumulation of intracellular lipid droplets in tumor cells." (PMID 26350211, 2016). "Consistent with this, BPTF expression in human tumours positively correlates with activation of c-MYC gene signatures." (PMID 26729287, 2016). "Among c-MYC-repressed miRNAs, tumor suppressor miR-15a/16-1 were first reported to be suppressed in chronic lymphoid leukemia (CLL) and found to target the anti-apoptotic protein BCL-2." (PMID 27494872, 2016). "Omomyc can stimulate MYC-induced apoptosis of NIH3T3 cells in a MYC-dependent mannerin vitro and of MYC-overexpressing tumor cells in a mouse model of K-Ras-driven lung adenocarcinoma." (PMID 27081479, 2016). "A gradual increase of MYC expression was detected in GC samples through tumor stages I to IV (p<0.008 for all analyses; Mann-Whitney test followed by Bonferroni correction)." (PMID 27863420, 2016). "MYC is an oncogene, which is found to be deregulated in different cancers and, amplification of MYC often correlates with tumour aggression and poor prognosis." (PMID 27339797, 2016). "Fortuitously, MYC-dependent tumor cell death can be induced by inhibiting the mitochondrial gene expression pathway using a variety of strategies, including treatment with FDA-approved antibiotics." (PMID 27590350, 2016). "We were unable to establish a similar assay for the MYC-coding region and therefore resorted to genotype and tumour gene expression data from the TCGA consortium." (PMID 27774982, 2016). "MYC and its upstream β-catenin are key oncogenic players that maintain the cell cycle under tumor-favorable conditions." (PMID 27447861, 2016). "Correlating with these findings, there was a significant correlation between the expression of active β-catenin and MYC in ALK + ALCL primary tumor cells." (PMID 27821172, 2016). "Consistently, 1p/19q co-deleted tumours with the highest MYC activity score had a worse prognosis (log-rank P value=0.01)." (PMID 27090007, 2016). "After evaluating tumor cells (10 random fields) derived from 3 cases, we found a highly significant correlation between the expression of MYC and active β-catenin (P < 0.0001) (400×)." (PMID 27821172, 2016).
tumor (continued). "MYC is a key regulator of cell growth and division, deregulation of MYC result in uncontrolled cell proliferation and tumor progression." (PMID 26735889, 2016). "While all of the tumor cells at both diagnosis and relapse shared the two SNVs in CREBBP and RGS11, five additional mutations in NRF1, MARCKS, USP11, ELK1, and MYC were detected at diagnosis." (PMID 26527318, 2016). "Even transient inactivation of MYC is sufficient to restore checkpoint mechanisms resulting in tumour regression, remodelling of the tumour microenvironment, and shutdown of angiogenesis." (PMID 26729287, 2016). "In particular, a striking enrichment in gene sets related to the MYC pathway was also observed in TCGA O1 tumours." (PMID 27090007, 2016). "In contrast, we observe that NR4A1 regulates a transcriptional profile dominated by proliferative genes, specifically a core MYC oncogenic signature, which is likely the primary mechanism of tumor suppression by NR4As." (PMID 26938745, 2016). "A number of studies have reported that short-term pharmacological inhibition of MYC using 10058-F4 or more potent analogs leads to tumor regressionin vivo." (PMID 27081479, 2016). "According to this theory, the promoters of all actively transcribed genes are occupied and activated by c-MYC in tumor cells expressing high levels of this transcription factor, leading to non-linear amplification of existing transcriptional activities." (PMID 27313991, 2016). "In our in vitro studies we observed potent anti-tumor activity of selinexor in MYC and BCL2/6 “double-hit” DLBCL, while the clinical responses were observed across all subtypes of NHL independent of genetic abnormalities." (PMID 27693556, 2016). "The search for critical targets in MYC-dependent tumor cells is exacerbated by the fact that during tumor development, cancer cells progressively evolve in a multistep process, thereby acquiring their characteristic features in an additive manner." (PMID 27313991, 2016). "Taken together, these results suggest that various molecular mechanisms concur to MYC activity in O1 tumours: genomic alterations, hypomethylation and down-regulation of its silencers mir34b and mir34c through hypermethylation of their promoter region." (PMID 27090007, 2016). "Additional MYC downregulation in the tumor cells of LP-DLBCL possibly explains the low tumor cell content in these cases." (PMID 27708232, 2016). "The most striking differential activity among the oncogenic pathways was observed in O1 tumours where several gene sets reflecting MYC activity were found among the most significantly deregulated gene sets (GSA score>1, P value<0.05)." (PMID 27090007, 2016). "At three hours post-dose MYC levels are suppressed to a similar extent in both tumor models, and the degree of MYC suppression correlates with savolitinib dose." (PMID 27472392, 2016). "Dinaciclib significantly inhibited the cyclinT1, CDK9, c-MYC, cyclin B1 and survivin protein expression levels in tumor tissues (n=3)." (PMID 27486754, 2016). "BET specific inhibitors have shown therapeutic potential in many different tumor models through multiple mechanisms, including down-regulation of c-MYC expression." (PMID 27259267, 2016). "A lack of MYC expression was confirmed in the majority of LP-DLBCL tested, whereas in conventional DLBCL, around 50% of the cases show MYC expression in more than 30% of the tumor cells." (PMID 27708232, 2016). "GGI, a gene signature that mainly measures tumor proliferation, was highly correlated with Oncotype DX, Gene70, modules describing proliferation (AURKA) and PTEN loss, and MYC and IGF1 pathway activation." (PMID 26934123, 2016). "In inducible c-MYC-driven models, established tumours regress upon withdrawal of ectopic c-MYC expression." (PMID 26729287, 2016).
tumor (continued). "c‐MYC regulates the expression of a number of genes, including genes involved in cell growth, cell cycle progression, differentiation, and apoptosis, and deregulated c‐MYC expression drives tumor formation." (PMID 27329485, 2016). "Immunofluorescence and immunohistochemistry assay were initiated to evaluate the expression of MYC and its correlation with its regulator by chi-square test analysis in human primary tumor cells." (PMID 27821172, 2016). "Inhibition of c-MYC using either siRNA or pharmacological intervention has been shown to limit tumor growth in vitro." (PMID 25576913, 2015). "These significant regions included MYC for the “all tumours” group and for one of the selections with split tumour pairs." (PMID 25955013, 2015). "The synergism between c-MYC and miR-17-19b, a truncated version of the miR-17-92 cluster, is well-documented during tumor initiation." (PMID 26555894, 2015). "MYC protein levels were significantly higher in HCC tissues than that in adjacent non-tumor tissues, (0.11 versus 0.46), (P < 0.01)." (PMID 25749381, 2015). "Several earlier studies have shown that over-expression and/or over-activation of certain genes such as PDGFRs and c-MYC in the tumor tissues of MB patients are correlated with an aggressive tumor phenotype and poor prognosis." (PMID 25576913, 2015). "MYC was the most frequently amplified gene in our study, with 27 of 109 (24.8%) cancers showing MYC amplification in at least one tumor spot." (PMID 25649416, 2015). "In this study, we first report the role of CSIG in tumor growth and the relationship between MYC and CSIG." (PMID 25749381, 2015). "At the end of experiment, histopathology of tumor sections, T cell immunophenotyping, tumor nitric oxide level, serum cytokine level and qPCR analysis on expression of iNOS, iCAM, NF-kB and c-MYC were performed." (PMID 26335427, 2015). "When tumor cells are exposed to hypoxia, a new equilibrium is sought between HIF1α and c-MYC for control over translation." (PMID 26501324, 2015). "The elevated protein translation observed in tumor cells is driven by constitutively expressed c-MYC." (PMID 26501324, 2015). "Second, the SRSF1 gene is a target of MYC, a potent oncogenic transcription factor overexpressed in many different tumor types that has pleiotropic effects on cancer cell biology." (PMID 26273603, 2015). "Genome copy number assessment of the FFPE tissue of this boy’s original tumor showed two significant events: amplification of the MYC locus and deletion at Xp11.2." (PMID 26380221, 2015). "This not only demonstrates the tissue specificity of BRD4 function, it indicates the feasibility of using BRD4 inhibitors and the ability of BRD4 to regulate target genes such as MYC will have to be evaluated in each tumor type." (PMID 25537515, 2015). "As an oncoprotein, c-MYC has been reported to maintain tumorigenicity and accelerate tumor growth in different cancer types." (PMID 26317998, 2015). "Over-expression of c-MYC promotes tumorigenesis while inhibition of c-MYC reduces tumor growth in vitro and in vivo." (PMID 25576913, 2015). "To investigate the effect of loss of HDAC2 function on tumor biology, we performed siRNA-mediated knockdowns of HDAC2 in MYC amplified cells." (PMID 25853389, 2015). "To clarify how CSIG affects the proliferation and cell cycle of HCC cells, we examined the protein levels of a number of important tumor-related genes, including MYC, PTEN, and so on." (PMID 25749381, 2015). "The protein level of CSIG and MYC was greater in tumor tissues of mice treated with SMMC7721-CSIG than SMMC7721-control." (PMID 25749381, 2015).
tumor (continued). "We confirm a number of previously published molecular changes associated with high risk disease, including MYC amplification, and NKX3-1, RB1 and PTEN deletions, as well as over-expression of PCA3 and AMACR, and loss of MSMB in tumour tissue." (PMID 26501111, 2015). "To clarify how CSIG affects the proliferation and cell cycle of HCC cells, we examined the protein levels of a number of important tumor-related genes, including MYC and PTEN." (PMID 25749381, 2015). "We used EMSA to detect constitutive NF-κB/STAT3 activity in BL- and MM-like neoplasms that spontaneously developed in single-transgenic IL6 (interleukin-6) or MYC (c-Myc) mice, or in double-transgenic IL6MYC mice." (PMID 25838973, 2015). "We also analyzed protein expression levels of Cyclin D1, which coordinates with c-MYC in tumor initiation and progression." (PMID 26046375, 2015). "Oncogenic genes such as c-MYC that are expressed at high levels in many types of cancers are tumor-inducing factors that prevent programmed cell death and cause uncontrolled cell proliferation." (PMID 26317998, 2015). "Additional copy number events were detected in some of the screened tumour samples, which included MYC and EMSY amplifications and PTEN exonic deletions." (PMID 26569395, 2015). "Western blot analysis performed on the expression profiles of the MTOR signal cascade in the tumor adjacent tissues revealed that the treated group expressed a lower level of MTOR/EIF4EBP1/YY1/MYC/SLC2A1 signaling than the untreated group." (PMID 25909713, 2015). "Amplification of the MYC locus was defined as the presence of increased number of MYC signals (more than 6) in tumor cells." (PMID 26682080, 2015). "Potentially combining MAPK pathway inhibitors with other tumor-specific inhibitors, such as agents targeting MYC signaling (in MYC-amplified tumors) has the potential to significantly increase the efficacy of therapeutic regimens." (PMID 26440310, 2015). "In some tumours, high c-MYC copy number is reflected in high c-MYC protein expression but in others the additional copies of c-MYC do not result in high levels of protein expression." (PMID 25531321, 2015). "Together with the previous findings of MYC-regulated lncRNAs, our results show that MYC tunes its oncogenic function by inducing oncogenic lncRNAs and repressing tumor-suppressor lncRNAs." (PMID 26003165, 2015). "For example, oncogenesis driven by MYC rendered non-transformed cells vulnerable to hypoxia-induced apoptosis; the degradation or cleavage of c-MYC under hypoxia allowed tumor cells to evade hypoxia-induced apoptosis." (PMID 26452058, 2015). "Aukema and colleagues defined DHL as a neoplasm characterized by a MYC rearrangement combined with another genetic abnormality, such as BCL2, BCL3, BCL6, or other genes." (PMID 26515759, 2015). "We derived and selected λ-MYC B lymphoma lines that, like the BL lines, retained the phenotypic characteristics, including pro-apoptotic propensity, of the tumor biopsy cells." (PMID 25702581, 2015). "Our group previously reported the presence of gains of chromosome 8 (on which the MYC gene is also located) in GC cases from Northern Brazil and in all GC cell lines established from neoplasias in this population." (PMID 26460485, 2015). "Although there was high variability in the PKM2/PKM1 ratios among the MYC+ tumor tissues, the mean ratio was significantly higher (P = 0.016, Mann-Whitney test) than in the non-amplified MYC tumors." (PMID 25970789, 2015). "MYC protein levels were increased in 85.7% (18/21) of HCC samples compared with adjacent non-tumor tissues." (PMID 25749381, 2015). "In mice, addition of CPI203 to lenalidomide therapy further decreased tumor burden, involving simultaneous MYC and IRF4 down-regulation and apoptosis induction." (PMID 25849938, 2015). "Apart from inducing cell proliferation and growth, the MYC transcriptional network regulates a large number of micro-RNAs (miRs) that function as oncogenes or tumor suppressor genes." (PMID 26416427, 2015).
tumor (continued). "Experimental model systems of MYC oncogene inactivation in various cancers have revealed molecular mechanisms of oncogene addiction, escape from oncogene dependence resulting in tumor recurrence." (PMID 26412380, 2015). "A number of microRNAs have recently been reported to repress MYC expression and function as tumour suppressors, including the let7 and miR-34 clusters as well as miR-145." (PMID 25869206, 2015). "Collectively, MYCLos are a newly identified class of MYC-regulated lncRNAs, with some of them having an oncogenic role (MYCLos 1–3) and others having a tumor suppressor role (MYCLos 4–6)." (PMID 27077133, 2015). "The proto-oncogene MYC, frequently overexpressed in various cancers, has a key role in tumor cell cycle regulation and tumor pathogenesis." (PMID 26003165, 2015). "Using our super-SILAC standard we explored the global proteome differences between human MYC amplified (MYC+, n = 3) versus non-MYC amplified (MYC−, n = 3) Group 3 primary tumor cells." (PMID 25970789, 2015). "The in situ hybridization performed later revealed clearly the presence of EBV in the tumour sample and showed a complex and unusual MYC gene rearrangement." (PMID 26089910, 2015). "Surprisingly, although increased reactive oxidative species (ROS) production is associated with up-regulation of glycolysis, we saw significantly lower levels of H202 in our MYC-amplified tumor cells (P < 0.01)." (PMID 25970789, 2015). "MYC was located in amplified regions of CFA13 associated with moderate to severe nuclear pleomorphism, high mitotic index and invasive growth into tumour stroma." (PMID 25955013, 2015). "Downregulation of a new miR-17/20 target, checkpoint kinase 2 (Chek2), increases the recruitment of HuR to c-MYC transcripts, resulting in the inhibition of c-MYC translation and thus interfering with in vivo tumor growth." (PMID 26555894, 2015). "In 2005, Kathryn O'Donnell and colleagues reported that the transcription factor c-MYC, one of the most common oncogenes in human neoplasms, was able to regulate the expression of the miR-17~92 cluster." (PMID 26226002, 2015). "On the other side, miR-17-92 cluster also can negatively regulate the oncogene E2F1 or MYC to inhibit cell cycle progression as the tumor suppressor gene." (PMID 24722426, 2014). "MAX mediates transactivation of pro-differentiation genes by virtue of suppressing activity of MYC, and it suppresses MYC-mediated activation of stemness-related genes, acting as a bona-fide tumor suppressor." (PMID 24722523, 2014). "CRCs with MYC over-expression demonstrated improved 5-year survival (93.2% vs. 57.3%), with the effect significantly modulated by the dominant effect of tumor stage, age at diagnosis and lymphovascular space invasion status on survival." (PMID 24503701, 2014). "In a recent study, we suggested that the high expression of MYC/MYCN is critical to the existence of stem cell-like tumor-initiating NB cells." (PMID 24190252, 2014). "Further, histochemical analysis of treated MYC-CaP/CR tumor tissue for AR expression revealed that both vehicle and docetaxel treated tumors displayed strong AR nuclear staining." (PMID 25072314, 2014). "Over time, the tumor suppressive signaling can be dismantled, perhaps by dysregulated MYC expression, allowing progression of the transformation process." (PMID 24675570, 2014). "The ectopic expression of MYC promotes its collaboration with HIF to confer metabolic advantages to tumor cells, which partly contributes to the Warburg effect." (PMID 24884974, 2014). "Most RCC result from Von Hippel-Lindau (VHL) tumor suppressor loss-of-function and subsequent gain-of-function of the oncogenic HIF-2alpha/c-MYC pathway." (PMID 24657971, 2014).